CD44 (CD44 molecule (IN blood group))
Diseases named in the same sentence as CD44 in open-access papers (continued):
Sharing a sentence is not in itself a finding about the gene and the disease.
breast carcinoma (continued). "For example, a previous study showed that blocking YB-1 protein expression delayed tumorigenesis in mice and that YB-1 was involved in the expression of stemness surface markers, including CD44, in breast cancer-initiating cells." (PMID 32206124, 2020). "SHH/SMO inhibitors have been shown to inhibit the CSCs of some cancers, including pancreatic cancer (ALDH+ cells), colon cancer (CD133+ cells), breast cancer (CD44 +CD24− cells) and gastric cancer (CD44+ cells)." (PMID 32962123, 2020). "For example, the transmembrane glycoprotein CD44 was up-regulated in tamoxifen-resistant breast cancer cells and enhanced their sensitivity to ErbB ligands and hyaluronan, thus promoting an adverse phenotype." (PMID 33324567, 2020). "Specifically, CCL2 production was impacted by the loss of CD44 in both the Hs578T and MDA-MB-231 cells, which is relevant to breast cancer, as CCL2 has been shown to recruit monocytes into the primary tumor and promote metastasis." (PMID 32455980, 2020). "In 2003, Al-Hajj showed that tumorigenic breast cancer cells significantly exhibited stem cell-like properties, such as CD44+/CD24/low." (PMID 32986353, 2020). "In breast cancer, the combined expression of CD44 and CD24, commonly reveals enrichment of the CD44−CD24+ and CD44+CD24Lo/− cell phenotypes in luminal and basal-like breast cancer cell lines, respectively." (PMID 32545405, 2020). "Most recently, CD44 was identified to significantly increase PD-L1 expression, enhancing immunosuppression by alleviating T cell enrichment in breast cancer and lung cancer." (PMID 33028341, 2020). "The present study thus evaluates the expression of CD44 as a surrogate marker for BCSCs by immunohistochemistry in primary HER2-positive breast cancer." (PMID 32986353, 2020). "Our results demonstrate that breast cancer cells synthesize and fragment HA and express CD44 on the cell surface." (PMID 32455980, 2020). "The number of MUC-1+/CD44+ TMPs detected in plasma samples from 12 out of 15 breast cancer patients post-chemotherapy was 3–4-fold higher than those at baseline." (PMID 33050539, 2020). "Based on the analysis of The Cancer Genome Atlas (TCGA), v10 is one of the most abundant variable exons in CD44, and its expression has been shown to be most highly correlated among the breast cancer specimens." (PMID 33143085, 2020). "Knockdown of the Notch pathway has resulted in radiosensitization of breast cancer cells, leading to cell death especially in CD44+ than in CD44- cells." (PMID 32660072, 2020). "CD44 is reported to be essential for prostate cancer and breast cancer cell adhesion and transendothelial migration, as well as for enhanced cancer cell adhesion to bone marrow endothelial cells." (PMID 33379338, 2020). "High levels of CD44 in serum are an independent prognosis indicator in primary breast cancer, since it correlates with overall survival and disease-free survival." (PMID 33224883, 2020). "TNBCs have the highest number of CD44+/CD24neg/low BCSCs when compared to the other molecular breast cancer subtypes." (PMID 32883003, 2020). "In several cancers, including breast cancer, CD44 and CD24 cell surface markers have been used to isolate CSCs; however, they should not be regarded as universal markers." (PMID 33233552, 2020). "Several established markers of breast cancer CSCs, including CD44+/CD24−/low phenotype and CD133, ALDH1, EpCAM, and nestin overexpression, have been correlated with poorer prognosis diagnosed patients." (PMID 33375383, 2020). "CD44-ICD has been shown to regulate the expression of numerous genes via its interaction with RUNX2 in breast cancer cells." (PMID 33062960, 2020). "Previous studies have confirmed that miRNAs play an important role in gene regulation in CD44+CD24−/low breast cancer stem cells (BCSCs)." (PMID 33008330, 2020).
breast carcinoma (continued). "further confirmed CD44-mediated regulation of glycolysis in breast cancer cells via LDH1 isoform upregulation by the CD44-activated c-Src/Akt/LKB1/AMPKα signaling pathway." (PMID 33335857, 2020). "A subpopulation (CD44+/CD24−/low) of breast cancer cells has been reported to have stem cell properties." (PMID 33255298, 2020). "6-Methoxymellein inhibits the proliferation, migration, and colony and mammosphere formation of breast cancer cells and decreases the subpopulation of CD44+/CD24− and the expression of c-Myc, Sox-2 and Oct4 proteins." (PMID 32977636, 2020). "CD44 plays essential roles in cancer progression of multiple tumor types, including breast cancer, lung adenocarcinoma, ovarian cancer, and glioblastoma." (PMID 33303029, 2020). "Cancer cells were incubated with PAA (0.2 mM) for 1 day and CD44+/CD24−-expressing population on breast cancer was tested." (PMID 33202749, 2020). "CD44 is of particular interest, as it is widely expressed in the tumor cells of breast carcinomas and has been shown to promote tumor growth and mediate drug resistance by maintaining cancer stem cell populations." (PMID 32455980, 2020). "Moesin phosphorylation was inhibited by CD44 de-crosslinking in breast cancer cells and Moesin shRNA knockdown attenuated the promotion of CD44 cross-linking on cell migration and invasion." (PMID 33292278, 2020). "According to the previous reports, CDKL2 is a newly discovered regulator enhancing EMT and increasing CD44-high subpopulation through upregulating ZEB1 expression in breast cancer." (PMID 33178818, 2020). "For instance, in vivo homophilic CD44-mediated CTC clustering of metastatic breast cancer cells in mice was largely inhibited by the administration of anti-CD44 neutralizing antibody, leading to decreased metastatic capacity." (PMID 32984308, 2020). "It is believed that the CD44+/CD24− population can enrich the CSC population in breast cancer cells." (PMID 33374889, 2020). "Although the effect of andrographolide on the BCSCs is quite remarkable, its CC50 value of 0.32 mM in the CD24-/CD44+ BCSCs is higher than the doses of most marketed drugs against breast cancer that are effective at a lower concentration." (PMID 33211707, 2020). "The in vitro cytotoxicity and cellular uptake of various formulations at pH 7.4 and 5.5 were evaluated on the mammospheres (MS), which were sorted by MCF-7 human breast cancer cell lines and identified to be a CD44+/CD24− phenotype." (PMID 32019122, 2020). "Recent reports have identified the interaction of RUNX2 with CD44-ICD on the promoter of the MMP-9 gene in breast cancer." (PMID 33062960, 2020). "SMO inhibitor cyclopamine decreased SMO, GLI and CD44 expression and reduced cell proliferation of breast cancer stem cells for chemoresistance." (PMID 32962123, 2020). "In solid tumors, first cancer stem cells were described as CD44 + CD24−/low lineage− in a breast cancer." (PMID 33424978, 2020). "Clinically, we found that the percentage of TMPs expressing CD44 was increased in plasma samples from breast cancer patients following chemotherapy when compared to baseline levels." (PMID 33050539, 2020). "In contrast to the CD44+/CD24−/low phenotype, which is rather associated with basal-like breast cancer, ALDH1 positive cells were found in basal-like, luminal and HER2 breast cancers." (PMID 32430004, 2020). "Many studies have verified the breast cancer stem cell line with the CD44+/CD24-/ALDH+ marker, and recently the high expression of aldehyde dehydrogenase (ALDH+) was associated to therapeutic resistance." (PMID 33680952, 2020). "In breast cancer, the dependency on glycolysis for CD44+ CSCs has been demonstrated by the enrichment of essential enzymes of glycolysis for maintaining cancer stem-like properties under hypoxic conditions." (PMID 33335857, 2020).
breast carcinoma (continued). "In breast and lung cancer cells CD44 was shown to be a key regulator of PD-L1 expression following shRNA-directed knockdown of CD44 in vitro and in vivo using a metastatic breast cancer xenograft mouse model." (PMID 33193345, 2020). "In studying the relationship between STAT3 and CSCs, Polyak and colleagues found that the IL-6/JAK2/Stat3 pathway is preferentially active in CD44+CD24− stem-enriched breast cancer cells, where it is required for their growth." (PMID 32391382, 2020). "After stratification of these specimens based on LIPH expression, we found that the percentage of CD44+/CD24− CSCs in LIPH + TNBC specimens was significantly higher than the percentage in the corresponding LIPH‐ breast cancer." (PMID 32618099, 2020). "Another study on breast cancer demonstrates that depletion of CD44 substantially hampers the aggregation of circulating tumor cells (CTCs) which contribute to cell migration, accompanied by down-regulation of p21-activated kinase 2 (PAK2)." (PMID 33303029, 2020). "In conclusion, in our study, we demonstrate that Musashi protein knockdown downregulates several important stem cell characteristics in breast cancer, including CD44, vimentin and GBX2, likely due to Notch pathway downregulation." (PMID 32245259, 2020). "After treatment with the medication, the proliferation of downregulated CD44+CD24− breast cancer stem cells decreased." (PMID 32684928, 2020). "These biotin-MBs targeted against CD44 receptors efficiently recognized luminal breast cancer cells in PBS, and were able to separate them from the CD44- basal-like breast cancer subset with higher sorting purity than other control MBs." (PMID 32098406, 2020). "Specifically, we found that production of the chemokine CCL2 by breast cancer cells was significantly decreased after depletion of either CD44 or HA." (PMID 32455980, 2020). "Specifically, in breast cancer, an enrichment in CSCs can be identified in vitro by the CD44+/CD24−/low profile and by the formation of mammospheres and by in vivo limiting dilution assays in mice models." (PMID 33396951, 2020). "In recent decades, BCSCs with the metabolic marker aldehyde dehydrogenases (ALDH) and marker CD44, a small subpopulation of breast cancer cells, have been found to display stem cell capacities, such as self-renewal, long-term repopulation and differentiation." (PMID 32570844, 2020). "In breast cancer, previous studies have shown CSCs identified by CD44 expression are involved in metastasis." (PMID 33233552, 2020). "In order to further evaluate in vivo the impact of P2Et in BCSC-enriched breast cancer models (triple negative and luminal), we analyzed the expression of CD44, CD24, EpCAM, CD49f and ALDH in human cell lines." (PMID 33184339, 2020). "JAK2/STAT3 signaling has been reported to be responsible for the maintenance of CD44+/CD24− stem like-cell populations isolated from human breast cancer cells." (PMID 32503225, 2020). "Upon the deletion of CD44 in breast cancer cells, we found decreased expression of genes involved in adhesion and cytokine activity." (PMID 32455980, 2020). "Breast cancer cells with high ALDH1 activity also demonstrate stem cell properties, namely by contributing to metastases and chemotherapy resistance, as well as the ones co-expressing P-cadherin, CD44 and CD49f, especially in basal-like breast cancer." (PMID 33396951, 2020). "CD44 is associated with a mesenchymal phenotype, while CD24 is associated with an epithelial phenotype in breast cancer." (PMID 33102470, 2020). "As to molecular phenotype in breast cancer, CSCs display CD44+/CD24- phenotype and high ALDH1 activity." (PMID 32547883, 2020). "Recently, a study identified a subpopulation of CTCs as metastasis-initiating cells from breast cancer patients who revealed high expression levels of stem cell markers, including CD44." (PMID 33207745, 2020). "Two well-known breast cancer stem-cell markers, CD44 and ALDH1 family member A1, were applied to verify this result." (PMID 33718103, 2020).
breast carcinoma (continued). "CD44 receptors are overexpressed on the surfaces of various tumor cells, including breast cancer and lung cancer, therefore, CD44 can be utilized as a cancer-targeting biomarker." (PMID 32290285, 2020). "A recent study reported that breast cancer stem cells were inhibited by benztropine mesylate in vitro by using stem cell markers such as aldehyde dehydrogenase activity, CD44+/CD24- phenotype, and the number of spheroids." (PMID 32102440, 2020). "The secretion of IL-6 is an important factor for CSC conservation as well as maintenance, and promotes the CD44+/CD24 low phenotype in breast cancer." (PMID 32391363, 2020). "We used a panel of organotropic metastatic breast cancer cells, which show an enrichment in a stem cell gene signature, enhanced CD44+/CD24−/low cell surface expression and increased mammosphere-forming efficiency (MFE)." (PMID 33396951, 2020). "To explore the predictive value of CD44 about chemoresistance in breast cancer patients, we assessed the levels of exosomal CD44 in serum samples by immunoelectron microscopy and flow cytometry analysis." (PMID 32760666, 2020). "We focused on the assessment of CTC heterogeneity in invasive-breast-cancer patients and the study of its stemlike features by the simultaneous usage of three markers (CD44 and CD24, ALDH1, or CD133), depending on N-cadherin expression." (PMID 32316333, 2020). "Administering neoadjuvant chemotherapy to patients with breast cancer raises the proportion of CD44+/CD24−/low in tumor cells and improves mammary development in vitro." (PMID 32684928, 2020). "Elevated CD44 expression levels were also found in TMPs from breast cancer patients treated with PTX." (PMID 33050539, 2020). "In breast cancer tumor cells, the localization of CD44 in lipid rafts, induced by palmitoylations on its cysteine residues, is considered to avoid the migration of these cells." (PMID 32271757, 2020). "Considering that ESRP1 is proposed as a master proto‐oncogenic mRNA splicing regulator responsible for CD44 alternative splicing in breast cancer, we did further genetic rescue experiments." (PMID 33240752, 2020). "A correlation has also been reported between CD44 expression and Breast Cancer (BC) cell proliferation, infiltration, angiogenesis, metastasis and prognosis." (PMID 32986353, 2020). "Then, another study indicates that CD24 and CD44 are cancer stem cells which can promote the development of breast cancer." (PMID 32558224, 2020). "The proportion of the CD44+/CD24−/low BCSC subpopulations were found to differ in breast cancer subtypes, where basal-like tumors show a higher proportion of these cells than luminal type tumors." (PMID 33327542, 2020). "Based on immunohistochemistry analysis of 125 breast cancer patient samples, it was found that CD44 protein level was positively correlated with poor disease-free survival (DFS) and OS." (PMID 33303029, 2020). "These dual drug-loaded HA micelles (HA-DOX-CDDP) exhibited significantly enhanced drug release under acidic conditions, and showed higher cellular uptake and stronger cellular growth inhibition than free drugs against 4T1 (CD44+) breast cancer cells." (PMID 32982750, 2020). "Human breast cancer cells (MDA-MB-231 cells) that have a high CD44 expression possess a potential activity of MMPs that facilitates invasiveness and CD44 depletion attenuated cell invasion through the reduction of collagen degrading enzymes." (PMID 32582701, 2020). "One therapeutic strategy for breast cancer treatment is targeting the CD44 surface marker on BCSCs using HA." (PMID 33255298, 2020).
breast carcinoma (continued). "At present, CD44 was identified as a stemness-related gene of several cancers including glioblastoma, breast cancer, hepatocellular carcinoma, colorectal cancer and acute myeloid leukemia." (PMID 32347296, 2020). "Xena browser analysis revealed a positive correlation between MTDH and the BCSC marker CD44 in breast cancer patients." (PMID 31979093, 2020). "We also demonstrated that breast cancer patients treated with paclitaxel chemotherapy exhibited increased CD44-expressing TMPs." (PMID 33050539, 2020). "In breast cancer, it was shown that cancer cells expressing CD44+/CD24−/low are particularly efficient in forming new tumors, showing the capacity to self-renew and to be therapy-resistant." (PMID 33396951, 2020). "STAT3 is centrally important for the maintenance of CD44+/CD24- CSCs in breast cancer, suppression of genes involved in cell proliferation correspondingly reduce STAT3 activation." (PMID 32754274, 2020). "PrPC is known to interact with CD44, and its expression correlates with resistance to chemotherapy in breast cancer cell lines." (PMID 33276687, 2020). "Next, we modified the MCF-7-derived exosomes loaded with siRNA against CD44 to observe the effects of targeting reduced CD44 expression in luminal A breast cancer cells." (PMID 32760666, 2020). "Recently, it was demonstrated that the human recombinant form of the proteoglycan 4 (PRG4) inhibits TGFβ-mediated invasiveness of breast cancer cells by binding to CD44 and affecting its downstream signaling pathway." (PMID 33199679, 2020). "An additional aid for identifying breast cancer stem cells is the expression of CD44+/CD24−/low cells." (PMID 33348862, 2020). "CD44 protein (upregulated in the serum pools from breast cancer patients vs. the pools from the control group patients) was found in the list of the 3,947 validated targets." (PMID 33224883, 2020). "As CD44 promotes breast cancer malignancy by interacting with cytoskeleton linker proteins, such as Ezrin, thus triggering the PI3K-related survival pathway, we next determined the role of Ezrin in CD44/HA induced resistance." (PMID 33024087, 2020). "In breast cancer, a cell population expressing ALDH1A1a and CD44 markers defines breast cancer stem cells (BCSCs)." (PMID 32796631, 2020). "Clinical data from 94 breast cancer patients reveal that CD44+/CD24−/low tumor cells were more common in CAIX+ than in CAIX− tumors." (PMID 32560271, 2020). "Along with being a primary HA receptor, CD44 is also highly expressed on breast carcinoma cells, suggesting that this transmembrane signaling protein is involved in the crosstalk between tumor cells and their surrounding environment." (PMID 32455980, 2020). "Similar peptide-based panning strategy has been used to isolate VHH against breast carcinoma proteins–Muc-1, CD44, and ScFv against human angiotensin-I and CXC chemokine receptor-2." (PMID 33425985, 2020). "Xena browser analysis also revealed a positive correlation between the MTDH and CD44 expression levels in The Cancer Genome Atlas (TCGA) breast cancer database (n = 1247, r = 0.05725, p-value = 0.04586)." (PMID 31979093, 2020). "Recently, we have shown the novel tGLI1 isoform to promote the glioma stem cell population via upregulation of CD44 and the breast cancer stem cell population through upregulation of CD44, Nanog, OCT4, and Sox2 (Section 6)." (PMID 32957513, 2020). "The binding of HA to its receptor CD44 triggers the expression of several stem cell markers and promotes drug resistance, cell invasion, and the reorganization of the cytoskeleton in breast cancer cells." (PMID 33371274, 2020). "Among solid tumors, CSCs was firstly identified in breast cancer as the cells with CD44+CD24low- phenotype." (PMID 31870099, 2019). "Switching of CD44 splice isoform in breast cancer cells has been reported to activate AKT signaling, and is essential for epithelial-mesenchymal transition (EMT) and cancer progression." (PMID 30935014, 2019).